MARF1 (meiosis regulator and mRNA stability factor 1)
Description:
Essential regulator of oogenesis required for female meiotic progression to repress transposable elements and preventing their mobilization, which is essential for the germline integrity. Probably acts via some RNA metabolic process, equivalent to the piRNA system in males, which mediates the repression of transposable elements during meiosis by forming complexes composed of RNAs and governs the methylation and subsequent repression of transposons. Also required to protect from DNA double-strand breaks (By similarity).
Synonyms: KIAA0430; LKAP; PPP1R34; LMKB
Tractability: PROTAC: ubiquitination databases record sites on it.
Gene: Protein-coding gene on chromosome 16 (15,594,302 to 15,643,209, reverse strand). Ensembl gene ENSG00000166783.
Subcellular location: Peroxisome
Subcellular location (Human Protein Atlas): Golgi apparatus; Vesicles
Gene Ontology:
Molecular function: protein binding; CCR4-NOT complex binding; nucleic acid binding; RNA binding; RNA nuclease activity
Biological process: female meiotic nuclear division; oogenesis; regulation of gene expression
Cellular component: membrane; peroxisome; cytoplasm
Genetic constraint (gnomAD): Loss-of-function variants: 19 observed, 165.08 expected, observed/expected ratio (o/e) 0.12, 90% interval 0.079 to 0.17. The upper end of that interval is the gene's LOEUF score, 0.17, which puts it in group 1 of 6, group 1 being the genes least tolerant of losing a copy. Missense variants: 1,696 observed, 2,172.8 expected, observed/expected ratio (o/e) 0.78, 90% interval 0.75 to 0.81. Synonymous variants: 841 observed, 836.68 expected, observed/expected ratio (o/e) 1.01, 90% interval 0.95 to 1.06.
Homologues: Orthologues: chimpanzee MARF1 (99% identical), macaque MARF1 (99% identical), rabbit MARF1 (93% identical), dog MARF1 (93% identical), pig MARF1 (92% identical), guinea pig MARF1 (91% identical), mouse Marf1 (86% identical), rat Marf1 (85% identical), rat LOC134485113 (80% identical), tropical clawed frog marf1 (67% identical), zebrafish MARF1 (50% identical), Drosophila melanogaster Marf1 (18% identical).
Diseases named in the same sentence as MARF1 in open-access papers:
MARF1 is named in the same sentence as 6 diseases in open-access papers, as found by Europe PMC text mining. Sharing a sentence is not in itself a finding about the gene and the disease. The quoted sentences say what the papers report.
female infertility (4 papers, 2018 to 2025). Diminished or absent ability of a female to achieve conception. "Mutations in MARF1 cause female infertility characterized by up-regulation of transcripts, defective cytoplasmic maturation, and meiotic arrest." (PMID 40721554, 2025). "A previous study showed that MARF1 is essential for the development of fertilization competent oocyte, and mutations lead to female infertility in mammals." (PMID 31744198, 2019). "To confirm that female sterility is due to loss of MARF1, we tested if transgenic MARF1 expression could rescue female fertility." (PMID 30279526, 2018).
Infertility (4 papers, 2014 to 2025). "Previous research has found that MARF1 can control meiosis in oocytes, and mutations in MARF1 can lead to infertility in female mice because oocytes fail to undergo meiosis and release immature eggs, indicating that this gene plays an important role in the process of oogenesis." (PMID 41007402, 2025). "Furthermore, the Wilcox test revealed a significant association of RPS9, DUT, CDKN2C and MARF1 genes with infertility in the red, blue, and turquoise modules." (PMID 35603216, 2022). "We found that the Marf1-eGFP-KI females ovulated mature oocytes with severe meiotic and developmental defects, and thus were infertile." (PMID 29353819, 2018). "Increased levels of PPP2cb may contribute to the observed meiotic arrest and infertility observed in Marf1−/− mice." (PMID 24755989, 2014).
MARF1 also shares sentences with these, for which no sentence is quoted: cancer (1 paper); neurodegenerative disease (1); oral squamous cell carcinoma (1); schizophrenia (1).